ELN (elastin)
Diseases named in the same sentence as ELN in open-access papers (continued):
Sharing a sentence is not in itself a finding about the gene and the disease.
emphysema (continued). "The significant role of elastin-derived peptides in the pathogenesis of pulmonary emphysema suggests that reducing their levels in the lungs may slow the progression of the disease." (PMID 40141701, 2025). "Furthermore, the aberrant cross-talk between macrophages and bronchial epithelial cells is essential for the degradation of elastin which contributes to emphysema, in which METTL3 plays a critical role." (PMID 39416774, 2024). "Uninhibited proteinases are able to cleave major extracellular matrix proteins, such as elastin and collagen (as well as fibrinogen), during neutrophil migration, damaging core lung structures - leading to the development of emphysema and the amplification of neutrophilic inflammation." (PMID 39015374, 2024). "In emphysema, inflammatory cells recruited in the alveolar spaces and the airways in response to chronic exposure to cigarette smoke secrete proteolytic enzymes such as elastase and MMPs which degrade elastin and other ECM components." (PMID 39830508, 2024). "It is also possible to directly affect the function of binding proteins, leading to disruption of barrier function, disorganizing the cross-linking of collagen and elastin, stabilizing the extracellular matrix and accelerating collagen and elastin damage leading to emphysema." (PMID 36674183, 2023). "This hypothesis is supported by the finding that emphysema severity, arterial stiffness, and skin elastin degradation in COPD patients significantly intercorrelate." (PMID 36835797, 2023). "Several studies have shown that loss of elastin rather than loss of fibrillar collagen due to proteolytic destruction is the cause of the disease and the development of emphysema." (PMID 36835197, 2023). "Arterial stiffness may be caused due to the imbalance between matrix metalloproteases and is related to elastin degradation, leading to emphysema in the lung and the systemic disruption of elastin in the vasculature." (PMID 37374082, 2023). "Additionally, cadmium has a direct impact on the adherence junction proteins, causing the synthesis of pulmonary MMP-2 and MMP-9, and accelerating collagen and elastin breakdown that results in emphysema." (PMID 37749472, 2023). "Consequently, MMP-12 and neutrophil elastase −/− mice were drastically protected from cigarette smoke induced emphysema due to reduced propensity for elastin degradation." (PMID 37001705, 2023). "As a result of their unique presence in elastin and the very low turnover of elastic fibers in normal tissues, DID may potentially serve as a biomarker for lung injury associated with pulmonary emphysema." (PMID 38164218, 2023). "Besides, other than directly damaging the lung matrix components such as elastin or collagen, oxides also interfere with the synthesis and repair of elastin, generating emphysema." (PMID 36051533, 2022). "Oligoclonal expansion of CD4+ T cells in lung tissue of emphysema patients has been shown and immune responses against elastin as a component of lung tissue have been supported by increased production levels of IFNγ from peripheral blood CD4+ T cells in COPD patients." (PMID 34271910, 2021). "Overexpress PDGF-A exhibited fatal pulmonary atelectasis at embryonic day 18.5 and could not survive after birth, with increased macrophages/eosinophils in airspaces and reduced elastin expression and emphysema." (PMID 32922942, 2020). "MMPs released from macrophages lead to the destruction of elastin and emphysema." (PMID 30781876, 2019). "Indicative of shared systems biology, it is notable that cutis laxa, a rare genetic condition caused by mutations in key structural components of elastic fibers (i.e. elastin, fibulin-4, and fibulin-5), manifests with excess inelastic skin and pulmonary emphysema." (PMID 31234847, 2019). "The emphysema phenotype, such as the multi-organ loss of tissue (MOLT), is currently receiving increased attention, and high elastin turnover could be associated with it, which has been shown by others." (PMID 30858579, 2019).
emphysema (continued). "First, an increase in elastase activity could be involved leading to a decrease in matrix protein elastin which seems to be related to the development of emphysema." (PMID 30134568, 2018). "Destruction of lung matrix, especially elastin, results in emphysema." (PMID 30134568, 2018). "Moreover, macrophages also produce excessive of proteases including MMPs, which are able to damage the elastin and other components of the alveolar wall followed by emphysema and decline in pulmonary function." (PMID 29765317, 2018). "However, the recruited inflammatory cells along with proteolytic enzymes act upon the anti-proteases (collagen and elastin) in alveolar region and inactivate them which in turn results in the destruction of alveolar septa and eventually develop emphysema." (PMID 28860943, 2017). "Even cigarette smoke (chronic obstructive pulmonary disease) and immune-allergical reactions (HP) both involve chronic lung inflammation, pathophysiological processes leading to emphysema may be different involving diverse collagen-elastin network impairment." (PMID 28614400, 2017). "The most widely accepted hypothesis for tissue destruction in emphysema is the impairment of elastin." (PMID 28614400, 2017). "The malignant cycle by elastin fragments contributes to emphysema progression." (PMID 26646821, 2015). "The relationship between arterial stiffness and emphysema might be due to connective tissue degradation or elastin degradation." (PMID 24251912, 2013). "Another hypothesis purports emphysema as an autoimmune disease affecting the lung and other systemic elastin-rich tissues in emphysema patients." (PMID 21647214, 2011). "Furthermore, knockout mice deficient in LO, thus failed in crosslinking of collagen and elastin, resulted in major development problems in the lung manifested by emphysema." (PMID 21318022, 2011). "Elastin has multiple cell hydrophobic repeating sequences with a core sequence of GxxPG that can induce a chemotactic response, and EDPs have been shown to drive disease progression in a mouse model of emphysema." (PMID 21647416, 2011). "As destruction of alveolar elastic fibres is implicated in the pathogenic mechanism of emphysema and elastin is a major component of the extracellular matrix, mice lacking elastin were generated." (PMID 15522115, 2004). "Notably, elastin (ELN) downregulation, particularly more pronounced in Delta infection, reflects loss of lung elasticity, consistent with pathological processes observed in emphysema." (PMID 41200555, 2025). "Furthermore, the levels of the unique elastin crosslinks, desmosine and isodesmosine, in blood, urine, and sputum may serve as biomarkers for the transition from pulmonary emphysema to interstitial fibrosis." (PMID 39519344, 2024). "The rapid acceleration of elastin breakdown with increasing alveolar wall distention supports the hypothesis that pulmonary emphysema is an emergent phenomenon involving a phase transition to an active disease state that is less amenable to therapeutic intervention." (PMID 38164218, 2023). "In addition, we show that Vangl2Lp/+ lungs exhibit many of the hallmarks of tissue damage, including an altered macrophage population, abnormal elastin deposition and elevated levels of the elastin-modifying enzyme, Mmp12, all of which are observed in emphysema." (PMID 28237967, 2017). "Hyperinflation, a feature of emphysema (a COPD subtype), occurs when elastin in airway walls is destroyed reducing recoil." (PMID 40244540, 2025). "Studies have shown that elevated DID levels correlate with elastin degradation in patients with chronic obstructive pulmonary disease (COPD), a disease complex including chronic bronchitis and pulmonary emphysema." (PMID 40075825, 2025). "Mechanical stress plays a central role in elastin degradation and remodeling of the ECM in pulmonary emphysema." (PMID 41303415, 2025).
emphysema (continued). "N.M further revealed that proteolytic degradation of elastin by C/EBP-β leaded to expansion of the airspace and development of emphysema." (PMID 39575390, 2024). "This enzyme plays a role in emphysema formation, such as in COPD, through collagen-IV and elastin proteolysis." (PMID 38203236, 2023). "Treatment of Fbn1 mgR/mgR mice with a monoclonal antibody directed against XGXXPG prevented elastin degradation, TGF-β signaling, upregulation of MMP-2 and −9, aortic macrophage infiltration, and suppressed the development of pulmonary emphysema." (PMID 37001705, 2023). "Unsurprisingly, expression of elastin degrading MMP-12 was inversely correlated with the carbon monoxide diffusing capacity of the lung and alveolar volume in patients with emphysema." (PMID 37001705, 2023). "In the lungs, the CS-induced imbalance between elastases/elastase inhibitors and oxidant/antioxidant levels can destroy elastin-rich structures leading to the onset of COPD, consisting of emphysema and chronic obstructive bronchitis." (PMID 35163482, 2022). "Stabilization of alveolar elastin and elastase inhibition by PGG can be seen as a combinatorial effect to preserve lungs from further damage in emphysema." (PMID 34537081, 2021). "It seems that MMP-12 plays a crucial role in this phenomenon: in a murine model it was shown that the enzyme breaks down the ECM component elastin, and MMP-12-null mice exposed to cigarette smoke avoided emphysema development." (PMID 30658596, 2019). "Pulmonary emphysema, a key symptom of COPD, results from the enzymatic destruction of lung ECM components including elastin and collagen, thereby decreasing tissue stiffness and stability." (PMID 30389913, 2018). "Emphysema is one form of COPD that results from the enzymatic destruction of lung extracellular matrix (ECM) components, including elastin and collagen, thereby leading to destruction of alveolar walls and airspace enlargement." (PMID 30389913, 2018). "While increased collagen levels may not be commonly associated with emphysema, in both samples from patients as well as in elastase-induced models of emphysema, thickened collagen fibrils can be found in areas of lung where the elastin has been degraded." (PMID 25303643, 2014). "The absence or inefficient function of α1AT in the lungs leads to uncontrolled function of elastase and elastin breakdown, resulting in respiratory problems such as COPD and emphysema." (PMID 22607686, 2012). "Measurements of elastin crosslinks in postmortem lungs from COPD patients provide evidence that an epidemic-like mechanism is responsible for elastic fiber injury and repair in pulmonary emphysema." (PMID 40141701, 2025). "However, in later stages of BPD, imbalanced deposition and altered cross-linking of elastin and collagen result in radiological and histological features resembling the “old BPD,” with fibrosis and emphysema." (PMID 40441240, 2025). "MMP-12 is known to be involved in the process of elastin degradation leading to emphysema, although exact mechanisms are not known." (PMID 38702427, 2024). "Interestingly, we also looked at desmosine, a crosslinker between elastin fibers that is usually used as a biomarker for elastin breakdown, and that has been found to be enhanced in the BAL fluid at this stage of emphysema." (PMID 33731130, 2021). "Moreover, hydrolysis of elastic fibers (elastin) by CatG and PR3 reduces the elasticity of the lung and represents a pathological feature of COPD as well as the development of emphysema." (PMID 34869231, 2021). "Furthermore, altered macrophage population, abnormal elastin deposition, and elevated levels of the elastin-modifying MMP12 were observed, which are similar to the markers of emphysema." (PMID 34829987, 2021).
emphysema (continued). "While we acknowledge the need to conduct further studies along this line to gain more insight into PGG’s involvement in MMP inhibition and elastin stabilization, this study gives us some preliminary positive outcomes for investigating PGG as a potential therapeutic for emphysema." (PMID 34537081, 2021). "In accordance with our findings, another study measuring plasma desmosine in the ECLIPSE cohort was not able to show a relationship between emphysema and elastin degradation." (PMID 30858579, 2019). "The enzymatic degradation of elastin referred to above is prominent in chronic obstructive pulmonary disease (COPD), where neutrophil-derived neutrophil elastase compromises the vessel wall integrity of pulmonary arteries resulting in emphysema." (PMID 26988843, 2016). "As reported in major clinical pathology of emphysema, the elastin fibers are degraded: as such, the airway wall does not recoil so strongly." (PMID 27176036, 2016). "In some major clinical conditions, the elastin fibers are degraded (emphysema): as such, the airway wall does not recoil so strongly." (PMID 27176036, 2016). "In a previous study we showed an increase in elastin in the PPE-exposed animals 28 days after the emphysema induction with no increase in type I fibrillin." (PMID 24886716, 2014). "The mice lacking elastin or elastic fiber proteins, such as fibrillin-1, show an emphysema-like lung at birth." (PMID 24886716, 2014). "In the absence of α1AT, elastase released from neutrophils, was not inhibited and lead to elastin breakdown and other symptoms like pulmonary problems such as emphysema or COPD in adults." (PMID 23705923, 2013). "In the absence of α1AT, elastase released by lung macrophages, was not inhibited and lead to elastin breakdown and pulmonary problems such as emphysema or COPD." (PMID 23705923, 2013). "After chronic exposure to TS for 7 months, they found that DBA/2 and C57BL/6J mice are more likely to develop emphysema and decreased lung elastin levels, while ICR mice did not develop these phenotypes." (PMID 22973236, 2012). "Using emphysema as the main hallmark of smoking-induced lung damage, peripheral blood CD4+ T cell immune responses to elastin consistently discriminated those with and without disease over 2 years of follow-up." (PMID 22969766, 2012). "By contrast, MMP12 expression decreased with age, suggesting that MMP12, a known contributor to cigarette smoke induced emphysema in murine models, is not the source of elastin turnover with murine aging." (PMID 21713037, 2011). "Although elastase activity is augmented in emphysema, there are evidence that elastase and elastin degradation may not represent the only pathway involved in the development of emphysema." (PMID 39830508, 2024). "Given its marked elastin-degrading activity, the overexpression of secreted CatS may be harmful, playing a deleterious role in the pathophysiology of COPD and emphysema, as supported by experimental results showing that CatS-deficient mice were more resistant to smoke-induced loss of lung function." (PMID 36670867, 2022). "We found that while some CD4+ T cells in emphysema had increased relative abundance of elastin positive tetramers without any stimulation, in most cases, up to 10-fold increase in T cell binding to the tetramers was found following 3 days of T cell stimulation with EFs (B and Figure A6 in Appendix)." (PMID 22969766, 2012). "Importantly, our findings demonstrate that, irrespective of lung function status, the presence of elastin-specific CD4+ T cells in the peripheral blood correlates with the degree of emphysema." (PMID 22969766, 2012). "Desmosine was also found to correlate with coronary artery calcification rather than emphysema in patients with COPD, indicating EDPs was more relevant to elastin of the vascular rather than the lungs." (PMID 33993833, 2021).
emphysema (continued). "Therefore, the development of COPD, particularly emphysema, was expected in HDM/RSV mice, but no such emphysema or elastin degradation was observed." (PMID 34703996, 2021). "As opposed to the linear appearance of elastin fibers in the alveolar compartment of WT mice, the elastin network in dox-treated IKTA mice appeared disorganized and clumped at the tips of alveolar ducts and loose/unraveled in inter-alveolar walls, as has been documented in human emphysema." (PMID 26756215, 2016).